INS (insulin)
Diseases named in the same sentence as INS in open-access papers (continued):
Sharing a sentence is not in itself a finding about the gene and the disease.
Insulin resistance (continued). "The triglyceride glucose (TyG) index, which was defined by incorporating serum glucose and insulin concentrations, was developed as a surrogate marker of insulin resistance." (PMID 34645432, 2021). "Etv5-knockout mice present impaired insulin secretion, which results in severe glucose intolerance and insulin resistance." (PMID 34716308, 2021). "Under diabetic conditions, however, increased insulin resistance impairs insulin biosynthesis and secretion." (PMID 33802741, 2021). "A further point that is pertinent to the issue of weight management is that LCDs are effective for reducing insulin levels and insulin resistance." (PMID 34336909, 2021). "T2DM is characterized by hyperglycaemia and insulin resistance, but also exhibits dysregulation of protein metabolism, resulting from impaired insulin secretion and/or insulin resistance." (PMID 34830706, 2021). "The role of miRNAs in mediating insulin signaling and resistance and their potential ability to therapeutically prevent or reverse insulin resistance is an area of increasing interest." (PMID 34831343, 2021). "T2DM is caused by a complex etiology characterized by resistance to insulin action, inadequate insulin secretion response, excessive glucose production in the liver, insulin resistance (IR), and decreased glucose processing capacity of muscle and fat cells." (PMID 34070604, 2021). "It improved hyperglycemia and oral glucose tolerance, promoted insulin signaling, improved insulin resistance, and improved lipid levels, etc., in high-fat diet-induced obese mice, these beneficial effects in vivo further demonstrated the promising therapy." (PMID 35069197, 2021). "Ectopic lipid accumulation in insulin-responsive tissues such as liver and skeletal muscle leads to insulin resistance via the accumulation of diacylglycerol (DAG) in the plasma membrane (PM) and subsequent translocation and activation of novel PKCs (nPKCs)." (PMID 33411692, 2021). "Group 4 had higher insulin level (6.05 ± 1.79 vs 4.14 ± 1.14 ng/ml, p = 0.038) and higher homeostasis model assessment of insulin resistance (HOMA‐IR) index (1.95 ± 0.73 vs 1.09 ± 0.37, p = 0.006) than group 1." (PMID 33904660, 2021). "Our model evidenced insulin resistance improvement by atorvastatin treatment, suggesting that atorvastatin-induced P-Akt increase is, at least partially, mediated through the insulin vasodilator response recovery." (PMID 34014280, 2021). "A lipid overload condition ceramide exerts an inhibitory effect on activation of protein kinase B (PKB/Akt) mediating in insulin signaling disruption, which favors hyperglycemia and supports insulin resistance (IR) development." (PMID 34830360, 2021). "The alleviation of insulin resistance was also shown by the restoration of high fasting blood glucose, insulin and HOMA-IR index." (PMID 33435282, 2021). "Specifically, 90% of adolescents with increased HOMA-IR and 91% of those with increased insulin levels, indicative of insulin resistance, were obese or overweight." (PMID 35053629, 2021). "In 2013, it was reported that MG53 is upregulated in models of insulin resistance and that it modifies insulin signaling by targeting the degradation of the insulin receptor β-subunit and of IRS1 by its ubiquitin E3 ligase activity." (PMID 34440850, 2021). "This meant that for these individuals, in addition to the PAE of exercise on insulin sensitivity, exercise training conveyed a chronic effect that protected them from aging-related insulin resistance." (PMID 34386716, 2021). "In an in vitro study, olanzapine inhibited IRS-1 and Akt phosphorylation induced by insulin and impaired insulin-signaling cascade, and this can be relevant for the peripheral insulin resistance." (PMID 33800403, 2021). "We confirmed that the knockdown of p85α expression in the liver promoted systemic insulin resistance, indicating the importance of its regulatory effect on insulin action." (PMID 33520119, 2021).
Insulin resistance (continued). "Serum adenosine deaminase (ADA) is an important enzyme that regulates the biological activity of insulin, and its levels are greatly increased in inflammatory diseases with insulin resistance." (PMID 34001220, 2021). "Third, SARS-CoV-2 induces the secretion of interferon-gamma and increases muscular insulin resistance and circulating insulin levels, which eventually increases the response of cluster of differentiation 8 cytotoxic T-cell (CD8 + T-cell)." (PMID 34441802, 2021). "Insulin resistance and abnormal insulin secretion are thought to be the major mechanisms of type 2 diabetes (T2DM) onset." (PMID 35392577, 2021). "Consistent with the decrease in body weight, fasting plasma insulin, fasting blood glucose, and insulin resistance (IR) were significantly reduced in IL-10fl/fl Foxp3-Cre+ mice compared with WT controls." (PMID 33351782, 2021). "With age, insulin resistance becomes more common and the ability of insulin to stimulate protein synthesis gradually weakens." (PMID 35002965, 2021). "For FT3, there were significantly positive correlations with systolic BP, obesity (BMI, WC, and WHtR), fasting insulin, insulin resistance (HOMA-IR) and hepatic steatosis (CAP and FLI) as well as negative correlation with age." (PMID 34794374, 2021). "Mouse models and humans with mutations suppressing the somatotropic axis show decreased body size and increased insulin sensitivity, which ultimately protects against diet-induced obesity, insulin resistance, and glucose intolerance." (PMID 33493548, 2021). "Some patients can expect to eliminate the need for insulin completely, over days or months, as insulin resistance resolves." (PMID 34434951, 2021). "Mechanistically, estrogens have been reported to protect against insulin resistance through activation of the estrogen receptor (ER) α pathway in insulin-sensitive tissues." (PMID 34177815, 2021). "The results demonstrated the presence of severe insulin resistance in T2DM mice by measuring serum insulin levels and determining the HOMR-IR index." (PMID 34691353, 2021). "Elevated insulin and glucagon are hallmarks of β-cell stress and insulin resistance, and NGOB mice showed clear β-cell compensation, with a robust increase in IGR that was lost in the T2D cohort." (PMID 33467110, 2021). "T2DM is a metabolic disorder characterized by sustained hyperglycemia resulting from impaired insulin production by pancreatic β cells, impaired insulin action (i.e., insulin resistance), or both." (PMID 33572228, 2021). "The phenotypes used to estimate insulin resistance were elevated fasting insulin levels (adjusted for body mass index [BMI]), decreased high-density lipoprotein (HDL) cholesterol, and elevated triglyceride levels." (PMID 34143812, 2021). "Rats treated for one day with DEX show pancreatic adaptation before the onset of marked insulin resistance with hyperinsulinemia and augmented glucose-stimulated insulin secretion (GSIS)." (PMID 33435513, 2021). "Insulin resistance, in children as in adults, is defined as a state in which insulin produces a subnormal biological response." (PMID 34444964, 2021). "The increased production of adipokines and inflammatory mediators significantly influences insulin signaling in insulin-responsive tissues, promoting systemic insulin resistance and hyperinsulinemia." (PMID 34940598, 2021). "On one hand, increased FFA production in obesity can inhibit insulin signalling contributing to insulin resistance." (PMID 33947164, 2021). "The characteristic pathological features of T2DM include insulin resistance and impaired insulin secretion." (PMID 34457002, 2021). "JNK1-dependent secretion of IL-6 in the adipose tissue caused increased expression of hepatic SOCS3, which induced degradation of molecules involved in the insulin signaling, resulting in hepatic insulin resistance." (PMID 33923817, 2021).
Insulin resistance (continued). "The reduction in the insulin sensitivity modulator allows for progression to insulin resistance, as previously discussed." (PMID 34769448, 2021). "The HOMA-IR and Matsuda insulin sensitivity indices have been widely utilized to quantify whole-body insulin resistance from fasting and average postprandial glucose/insulin levels, respectively." (PMID 33788828, 2021). "Ectopic accumulation of lipids in the skeletal muscle also induces inflammation, oxidative stress, and lipotoxicity, impairing insulin‐dependent glucose uptake and mitochondrial function, overall contributing to insulin resistance." (PMID 34319011, 2021). "Moreover, a number of studies have found that diets high in BCAA and protein in general may increase the risk of insulin resistance by blocking intra-cellular insulin signaling pathways and increasing plasma glucose levels via gluconeogenesis, although opposite effects were reported elsewhere." (PMID 33805161, 2021). "With varying degrees of insulin resistance there is incremental shifting in the balance between insulin’s vasodilator and vasoconstrictor actions." (PMID 34299190, 2021). "Deregulation in the insulin-AKT pathway leads to the development of the insulin resistance in adipocytes." (PMID 34225729, 2021). "TNF-α was reported to be high in the adipose tissue of obese individuals, and its level was correlated positively with insulin resistance as it interferes with the insulin signalling transduction via serine-phosphorylation of IRS-1." (PMID 33557218, 2021). "The cycle works via insulin-stimulated fat synthesis and adipose tissue initiating the synthesis of inflammatory markers, which then lead to augmented insulin resistance." (PMID 34063822, 2021). "Gradually increasing insulin levels during HFD indicate a compensation of beginning insulin resistance via higher insulin secretion to maintain physiological glucose levels." (PMID 33864446, 2021). "Insulin resistance (IR) is a condition characterized by a subnormal physiological response to normal insulin concentrations, with increased quantities of insulin produced to maintain adequate intracellular glucose concentrations." (PMID 33958992, 2021). "Women who develop gestational diabetes are unable to produce an adequate amount of insulin to maintain euglycaemia, and exhibit greater insulin resistance with resultant glucose intolerance." (PMID 35128441, 2021). "Several lines of evidence suggest that reduced insulin clearance is a compensatory response to insulin resistance." (PMID 34206745, 2021). "Hypoglycemia and insulin resistance are among the side effects of the conventional, widely used anti-diabetic treatment including oral hypoglycemic drugs and insulin injections." (PMID 34568337, 2021). "Insulin resistance is defined as the insufficient effect of insulin on tissues, and is measured using the HOMA-IR method." (PMID 33705641, 2021). "FGF21 regulates glucose and lipid metabolism in adipose tissue through endocrine pathways, improves insulin sensitivity and insulin resistance, and stimulates glucose uptake in skeletal muscle through GSIS." (PMID 33588950, 2021). "Obesity-linked insulin resistance and hyperinsulinemia results in elevated level of unbound IGF-1 protein in blood, with triggering of the insulin and IGF-1 receptors signal transduction pathways that eventually promotes tumor growth." (PMID 34535145, 2021). "Insulin resistance decreased in our aquatic exercise group due to post-exercise reductions in fasting blood glucose and insulin levels." (PMID 33918160, 2021). "This difference is reflected by a considerable proportion of patients with higher BMI, higher insulin levels and particularly elevated insulin resistance as assessed by the HOMA-IR index." (PMID 33499061, 2021). "The levels of fasting insulin and homeostatic model assessment for insulin resistance (HOMA-IR) were significantly promoted in the HFD group, and inhibited by curcumin treatment." (PMID 34818970, 2021).
Insulin resistance (continued). "The separation between insulin-resistant or insulin-sensitive individuals was made after a quantitative insulin-sensitivity check index (QUICKI) with a cut-off point of <0.33 to have insulin resistance and >0.33 to have normal insulin sensitivity." (PMID 34684349, 2021). "More recently, insulin resistance and hyperandrogenemia have come under the spotlight as key players in the pathogenesis of this complex disorder; insulin sensitizing agents have attained a central place in PCOS management." (PMID 34063169, 2021). "Aged mice exhibited impaired glucose tolerance and insulin resistance and showed higher serum levels of insulin and leptin and lower levels of adiponectin." (PMID 34143796, 2021). "Cytokines such as TNF-α, IL-6 and IL-1β are responsible for producing insulin resistance by reducing insulin secretion from the pancreatic β-cells and reducing the insulin utilizing ability of cells." (PMID 34912298, 2021). "In contrast, the insulin tolerance test/glucose tolerance test (ITT/GTT) showed impaired insulin resistance in the CLA-exposed mice compared to the control, in parallel with the elevated blood insulin levels." (PMID 34722605, 2021). "Two hallmarks of endothelial dysfunction observed in type 2 diabetes are vascular insulin resistance, i.e. impairment of vascular insulin signaling, and increased transendothelial transport of FFAs." (PMID 34214082, 2021). "Both HFD-induced WAT insulin resistance and hepatic insulin resistance have an insulin signaling defect at the level of IRK activation." (PMID 33411692, 2021). "Weight gain and obesity mediates most of its direct medical sequelae through worsening insulin sensitivity and, as such, the development of insulin resistance (IR)." (PMID 33430419, 2021). "A high WHR can be used as an indirect marker of a high testosterone/estrogen ratio and, possibly and most importantly, of insulin resistance and high fasting insulin, pro-insulin and C-peptide levels in women." (PMID 33479372, 2021). "KEGG pathway analysis showed that these genes were mainly enriched in Insulin resistance, Insulin signaling pathway, AMPK signaling pathway, and PI3K−Akt signaling pathway." (PMID 33705353, 2021). "Functionally, PKD3 suppressed insulin signaling, as indicated by the reduced Akt and mammalian target of rapamycin complex 1 and 2 (mTORC1 and mTORC2) activities, and promoted insulin resistance." (PMID 33807058, 2021). "Insulin resistance is a clinical condition in which insulin exerts a biological effect lower than expected and, in most cases, it is associated with metabolic abnormalities such as hyperglycaemia and hypertriglyceridemia." (PMID 33947164, 2021). "In mice, SIRT3 plays a crucial role in maintaining the skeletal muscle insulin action, as well as in protecting against the effects of insulin resistance during HFD, through facilitation of glucose disposal and mitochondrial function." (PMID 33806509, 2021). "Insulin resistance is a metabolic disorder, and the MAM has been shown to be a hub for insulin resistance in three key insulin-targeting tissues or cells: the liver, adipocytes, and skeletal muscle." (PMID 33917091, 2021). "Whereas, type 2 diabetes (T2D) has historically been considered to be on the other end of the spectrum resulting from insufficient insulin output and insulin resistance unrelated to autoimmune destruction of pancreatic β-cells." (PMID 33981301, 2021). "As for the serum metabolic parameters, the CAF diet induced an increase in circulating levels of triacylglycerides, insulin, insulin resistance indicated by the HOMA-IR (p < 0.05), and leptin (p < 0.001), compared to the STD group." (PMID 34960026, 2021). "Due to extreme obesity and high insulin requirement, indicating insulin resistance, he was treated with metformin 850 mg BID for a decade until 18 years of age, but the treatment failed to provide any significant effect." (PMID 34177811, 2021).
Insulin resistance (continued). "T2DM results from insulin resistance (cells less responsive to the insulin actions) and/or insufficient insulin production from pancreatic beta cells." (PMID 34234885, 2021). "BCAAs are involved in several metabolic pathways of insulin resistance, and studies have shown that BCAAs reduce insulin secretion through their effects on pancreatic β-cells." (PMID 34658643, 2021). "On the other hand, the decrease in glucose use by the muscle develops chronic hyperglycemia that perpetuates insulin resistance and in turn promotes increased insulin secretion." (PMID 33928108, 2021). "Supplementation of VS extract for 17 weeks significantly decreased body weight gain, fat weight, fasting glucose, insulin, homeostasis model assessment of insulin resistance (HOMA-IR), and triglyceride levels in high-fat diet (HFD)-fed C57BL/6J mice." (PMID 33671428, 2021). "Recent studies showed heterogeneity of type 2 diabetes and GDM with insulin secretion driven subtypes being different compared to insulin resistance driven subtypes." (PMID 34801028, 2021). "Insulin resistance develops in key insulin target tissues, including muscle, and is the result of altered fatty acid transport and oxidation, intramyocellular lipid accumulation, and reduced mitochondrial oxygen uptake in skeletal muscle." (PMID 34959870, 2021). "Leptin also reversed lipodystrophy-induced insulin resistance and diabetic complications by regulating insulin signaling in mice." (PMID 34631690, 2021). "Acute fasting can improve insulin signaling, but reduction of food intake during long periods can augment insulin resistance." (PMID 34827732, 2021). "The effect of sirtuin activation on insulin resistance was further validated by performing an in-vitro 2-NBDG uptake assay on palmitate-induced insulin-resistant cardiomyoblast (H9c2) cells." (PMID 33668369, 2021). "Type 2 diabetes (T2DM) is developed when their balance has deteriorated, i.e., insulin secretion cannot overcome increased insulin resistance, resulting in T2DM." (PMID 34834527, 2021). "Its dietary supplementation with avicularin as an oral insulin-sensitizing agent also potentiated the reversal in weight gain during insulin resistance." (PMID 33953863, 2021). "Multiple studies have specified that Akt2 is responsible for insulin-dependent glucose uptake in humans as well as rodents, and its dysfunction is related to insulin resistance and impaired glucose tolerance, which goes hand in hand with our study." (PMID 34360895, 2021). "The IVGTT, assessing simultaneously insulin sensitivity and glucose-induced insulin secretion, showed that AHI was associated with insulin secretion and Insulin resistance, supporting the previously reported association between OSA and T2DM4." (PMID 33574418, 2021). "They, together with resident macrophages, provide signals (e.g., PDGF) driving β-cell hyperplasia to overcome insulin insufficiency adapting to early weight gain and the development of insulin resistance." (PMID 33801681, 2021). "In skeletal muscles, glucocorticoid excess can inhibit the translocation of glucose transporter type 4 to the plasma membrane in response to insulin, resulting in insulin resistance." (PMID 34475697, 2021). "Fasting plasma insulin was elevated, likely as a response to the insulin resistance, but showed impaired GSIS response, suggesting the presence of beta cell dysfunction in the absence of α-syn." (PMID 34393754, 2021). "Given their suppression of insulin signal pathways and interference with the anti-inflammatory effects of insulin, they are potential mediators of insulin resistance." (PMID 34658643, 2021). "LPS can initiate pro-inflammatory cytokine formation, directing to impaired insulin reactivity and inauguration of insulin resistance-related metabolic disorders." (PMID 33924088, 2021).